XTBD1 (XRN2 binding domain containing 1)
Synonyms: CDKN2AIPNL; MGC13017; C2AIL
Tractability: PROTAC: ubiquitination databases record sites on it; its protein half-life has been measured.
Gene: Protein-coding gene on chromosome 5 (134,402,065 to 134,411,881, reverse strand). Ensembl gene ENSG00000237190.
Gene Ontology:
Molecular function: protein binding
Genetic constraint (gnomAD): Loss-of-function variants: 6 observed, 7.23 expected, observed/expected ratio (o/e) 0.83, 90% interval 0.45 to 1.59. That is too few expected variants to judge how well the gene tolerates losing a copy. Missense variants: 105 observed, 108.53 expected, observed/expected ratio (o/e) 0.97, 90% interval 0.82 to 1.14. Synonymous variants: 45 observed, 50.84 expected, observed/expected ratio (o/e) 0.89, 90% interval 0.7 to 1.13.
Homologues: Orthologues: chimpanzee CDKN2AIPNL (100% identical), dog CDKN2AIPNL (99% identical), macaque CDKN2AIPNL (99% identical), rabbit CDKN2AIPNL (98% identical), guinea pig CDKN2AIPNL (97% identical), pig CDKN2AIPNL (97% identical), mouse Cdkn2aipnl (97% identical), rat Cdkn2aipnl (96% identical), zebrafish cdkn2aipnl (48% identical), tropical clawed frog cdkn2aipnl (47% identical), Caenorhabditis elegans paxt-1 (26% identical), Drosophila melanogaster CG31301 (22% identical). Paralogues in human: CDKN2AIP (41% identical), NKRF (7% identical).
Diseases named in the same sentence as XTBD1 in open-access papers:
XTBD1 is named in the same sentence as 2 diseases in open-access papers, as found by Europe PMC text mining. Sharing a sentence is not in itself a finding about the gene and the disease.
XTBD1 shares sentences with these, for which no sentence is quoted: cancer (1 paper); tumor (1).